IL1R1 (interleukin 1 receptor type 1)
Diseases named in the same sentence as IL1R1 in open-access papers (continued):
Sharing a sentence is not in itself a finding about the gene and the disease.
kidney damage (4 papers, 2024 to 2025). "Thus, exaggerated IL-1β production and release by IL-1R1-deficient myeloid cells in response to multiple pro-inflammatory stimuli other than IL-1β aggravated the kidney damage in mouse AKI model." (PMID 40486517, 2025). "The analysis revealed high blood urea and macroalbuminuria (ACR > 300 mg/g) at 48 h p.i. in the Il1r1-/- mice, indicating that they suffered from severe kidney damage at that time point." (PMID 40097388, 2025). "In contrast, selective deletion of IL-1R1 in myeloid cells exacerbated kidney damage in kidney ischemia/reperfusion (I/R) injury model of AKI suggesting that IL-1 signaling in myeloid cells may act as a negative feedback loop to dampen excessive inflammation." (PMID 40486517, 2025). "However, no signs of kidney damage were observed at 10 h p.i., and only slight microalbuminuria (ACR > 30 mg/g) was seen at 24 h p.i. in the Il1r1-/- mice." (PMID 40097388, 2025).
knee osteoarthritis (4 papers, 2017 to 2023). "IL1R1, encoding interleukin 1 receptor type 1, is located in the IL-1 gene cluster and is involved in the pathogenesis of hand, hip, and knee osteoarthritis (OA) in different ethnicities." (PMID 27980229, 2017). "It has also been suggested that IL1R1 is involved in the pathogenesis of hand, hip, and knee osteoarthritis." (PMID 30287499, 2018).
leukemia (4 papers, 2021 to 2025). A malignant (clonal) hematologic disorder, involving hematopoietic stem cells and characterized by the presence of primitive or atypical myeloid or lymphoid cells in the bone marrow and the blood. "GAS6-AS1 promote the cooperation of YBX1 with MYC, leading to upregulation of downstream target genes associated leukemia progression, including IL1R1, SRC and RAB27B." (PMID 34753494, 2021). "We revealed that GAS6-AS1 directly binds Y-box binding protein 1 (YBX1) to facilitate its interaction with MYC, leading to MYC transactivation and upregulation of IL1R1, RAB27B and other MYC target genes associated with leukemia progression." (PMID 34753494, 2021).
lung disease (4 papers, 2012 to 2020). "Genes showing altered expression include a number of genes known to play important roles in lung disease such as α1-antitrypsin (SERPINA1), transforming growth factor β 1 (TGFβI), interleukin 1 receptor 1 (IL1R1) and IL6, IL8, IL1B, IL1A." (PMID 28335732, 2017).
lupus (4 papers, 2010 to 2023). "Therefore, we studied the ROS production and IL-1R1 expression in both spontaneous and induced lupus models." (PMID 37922035, 2023). "Thus, based on the IMQ-induced lupus model, we found an intrinsic increase in IL-1R1 expression and extrinsic release of ROS in CX3CR1+ macrophages responses to P140 treatments." (PMID 37922035, 2023).
lymphoma (4 papers, 2012 to 2022). A malignant (clonal) proliferation of B- lymphocytes or T- lymphocytes which involves the lymph nodes, bone marrow and/or extranodal sites. "Using flow cytometry, we found that knockdown of either gene significantly induced PEL cell apoptosis, which was further confirmed by the increased cleavage of PARP, Caspases-3 and -9, these major apoptosis markers from IL1R1 or IL1RAP knockdown lymphoma cells." (PMID 36457850, 2022). "By applying a combination of various prediction algorithms, we identified the 3′-UTR of c-FOS as a potential target for miR-181a and miR-181b (down-regulated the in EBV-associated lymphomas), CD44 as a potential target of miR-20a and miR-106a, and the IL1R1 as a target of miR-205 and -125a." (PMID 22870299, 2012).
memory impairment (4 papers, 2019 to 2023). "In addition, AβOs failed to cause alterations in expression of mitochondrial dynamics proteins or memory impairment in Il1r1−/− mice." (PMID 33612100, 2021). "While i.c.v. infusion of AβOs induced NOR memory impairment in wild-type (WT) mice, AβOs failed to impact memory in Il1r1−/− mice either 24 h or 7 days post-infusion." (PMID 33612100, 2021).
ovarian carcinoma (4 papers, 2005 to 2025). A malignant neoplasm originating from the surface ovarian epithelium. "The top distinctive genes for the proliferation metaprofile include, besides previously used markers, numerous genes related to malignancy and ovarian cancer progression, in particular cytokines and their receptors: CXCL1, IL1A, CXCL8, IL1B, IL1R1, and IL1R2." (PMID 29362714, 2017).
Ureteral obstruction (4 papers, 2015 to 2025). Obstruction of the flow of urine through the ureter. "Additionally, the genes encoding Il1r1 in the damaged proximal tubules were activated in both IR-induced and unilateral ureteral obstruction–induced (UUO-induced) CKD models." (PMID 40729113, 2025). "Numerous studies have established an overall detrimental role of IL-1R1 in kidney injury, as global genetic deletion of IL-1R1 reduces AKI and/or kidney fibrosis following I/R, unilateral ureteral obstruction, cyst formation, and cisplatin AKI." (PMID 38693918, 2024).
abscess (3 papers, 2011 to 2019). An inflammatory process characterized by the accumulation of pus within a newly formed tissue cavity which is the result of a bacterial, fungal, or parasitic infection or the presence of a foreign body. "Further abscess formation and the loss of surrounding bone around infected teeth were shown to be greater in IL1R1-null mice than wild-type controls." (PMID 21261944, 2011). "WT mice have MPO+ cells that surround and encompass the abscess, whereas Il1r1-/- mice show extensive MPO+ staining throughout the femur." (PMID 30978245, 2019). "We therefore hypothesized that the delay in bacterial clearance in Il1r1-/- mice subjected to osteomyelitis was related to differences in abscess maturation and neutrophil abundance." (PMID 30978245, 2019). "Disorganized abscess architecture in Il1r1-/- infected femurs may indicate improper neutrophil mobilization without IL-1R signaling as an underlying mechanism for the inability to control bacterial burdens." (PMID 30978245, 2019). "Il1r1-/- mice with osteomyelitis have differential MPO staining in comparison to WT controls, suggesting these mice have disorganized abscess structure." (PMID 30978245, 2019).
bipolar disorder (3 papers, 2014 to 2021). A disorder of the brain that causes unusual shifts in mood, energy, activity levels and the ability to carry out day-to-day tasks. "In bipolar disorder, cortical mRNA and protein levels of IL1β and IL1 receptor 1 (IL1R1) are elevated." (PMID 34911938, 2021).
Breast Invasive Carcinoma (3 papers, 2020 to 2024). "Dendritic cells showed a significant (Spearman’s, p < 0.05) positive correlation with IL1R1, ILRN, and ILRAP in breast invasive carcinoma-Basal and Luminal A patients." (PMID 39201290, 2024).
Crohn disease (3 papers, 2016 to 2025). A gastrointestinal disorder characterized by chronic inflammation involving all layers of the intestinal wall, noncaseating granulomas affecting the intestinal wall and regional lymph nodes, and transmural fibrosis. "Our data showing a relationship between SMAD7 and IL-1R1 expression in PSCs is also consistent with recent data demonstrating decreased inflammation and clinical benefits for patients with active Crohn’s disease after blocking SMAD7 by a SMAD7 anti-sense oligonucleotide." (PMID 27473228, 2016).
dry eye (3 papers, 2013 to 2021). "We tested the therapeutic potential of topical IL-1R1 antagonist anakinra as a treatment for aqueous-deficient dry eye in a spontaneous mouse model of autoimmune dry eye." (PMID 24068863, 2013). "We used Aire-deficient mice as a model of autoimmune-mediated aqueous-deficient dry eye that mimics the clinical characteristics of SS-KCS to demonstrate the therapeutic potential of the topically applied IL-1R1 antagonist anakinra." (PMID 24068863, 2013). "With activation of IL-1 signaling an essential step in the pathogenesis of autoimmune KCS, the next step was to test whether local inhibition of the IL-1R1 pathway provided an effective therapy for aqueous-deficient dry eye." (PMID 24068863, 2013). "We compared the effect of commercially available IL-1R1 antagonist, anakinra (50 μg/mL concentration) to that of carboxymethylcellulose (CMC) vehicle control as a treatment for dry eye." (PMID 24068863, 2013).
emphysema (3 papers, 2015 to 2024). "Therefore, the upregulation of BLNK and IL1R1 may be associated with airway inflammation rather than emphysema formation." (PMID 38203236, 2023). "Regarding the upregulated DEGs in COPD, CD109, B cell linker (BLNK), interleukin-1 receptor type 1 (IL1R1), CD1A, and carboxypeptidase A3 (CPA3) are related to T-helper cell type 2 (Th2) inflammation, but not to emphysema formation." (PMID 38203236, 2023).
Glucose intolerance (3 papers, 2022 to 2024). Glucose intolerance (GI) can be defined as dysglycemia that comprises both prediabetes and diabetes. "We found that IL-1R1 deficiency exacerbates MS in HFD-fed mice, increasing body fat and promoting glucose intolerance." (PMID 39203559, 2024).
hand osteoarthritis (3 papers, 2010 to 2019). "(2010) indicated that four SNPs (rs1465325, rs956730, rs3917225, and rs2287047) in the IL1R1 gene provided evidence for association with hand osteoarthritis." (PMID 30623603, 2019).
Hypertension (3 papers, 2019 to 2022). The presence of chronic increased pressure in the systemic arterial system. "One approach used short-hairpin RNA (shRNA) interference targeting IL-1R1 in the paraventricular nucleus (PVN), leading to reduced local IL-1R1 expression and downregulated sympathetic activity and improved myocardial remodeling, two important mechanisms underlying hypertension." (PMID 35163653, 2022). "Silencing macrophage-specific expression of MyD88, the molecular adaptor protein downstream of IL-1R1 stimulation, also disrupted the progression of PH in mice, leading to the speculation that the IL-1R1/MyD88 interaction is vital for facilitating signaling events that lead to hypertension." (PMID 34445357, 2021).
immunodeficiencies (3 papers, 2017 to 2021). "The importance of CD4+ T cells, TNF-α, IFN-γ, IL-12p40, together with the IL-1/IL-1R1 pathway, in host resistance to intracellular Mtb infection is evident from animal models and human inherited and acquired immunodeficiencies." (PMID 32069329, 2020).
infectious colitis (3 papers, 2013 to 2021). A viral or bacterial infectious process affecting the large intestine. "LTi-like cells require IL-1R1 for production of protective cytokines and confer protection in infectious colitis, and their cell numbers in the colon depend upon having a microbiome." (PMID 23750260, 2013). "Cells that express IL1-R1 are an important source of IL-22, which is in turn required for the coordination of effective responses against Salmonella owing to its ability to drive protective cytokine production and to prevent infectious colitis." (PMID 34222406, 2021).
osteomyelitis (3 papers, 2019 to 2022). An acute or chronic inflammation of the bone and its structures due to infection with pyogenic bacteria. "IL-1R1 cytokines are major influencers of bone pathology during osteomyelitis and, more generally, in inflammatory bone loss." (PMID 36226943, 2022). "Previous findings in our model of osteomyelitis corroborate the importance of IL-1R1 cytokines in bacterial containment during infection." (PMID 36226943, 2022). "To elucidate the cellular changes driving differences in bone remodeling between WT and Il1r1-/- mice, we next analyzed trabecular bone remodeling during osteomyelitis." (PMID 30978245, 2019). "In contrast to the extreme systemic morbidity observed in MyD88-/- mice suffering from osteomyelitis, Il1r1-/- mice had less morbidity when compared to WT mice, in that they lost significantly less weight over the course of infection." (PMID 30978245, 2019). "Therefore, the data suggest that Il1r1-/- mice with S. aureus osteomyelitis have altered neutrophil responses, indicated by the significant decrease in relative neutrophil abundance at two timepoints post-infection." (PMID 30978245, 2019). "We subjected WT and Il1r1-/- mice to S. aureus osteomyelitis." (PMID 30978245, 2019). "Collectively, these data indicate that during S. aureus osteomyelitis, Il1r1-/- mice exhibit significantly altered cortical bone remodeling, with increased reactive bone formation, altered callus architecture, and greater cortical bone loss at the site of infection." (PMID 30978245, 2019).
pancreatic ductal adenocarcinoma (3 papers, 2014 to 2024). An infiltrating adenocarcinoma that arises from the epithelial cells of the pancreas. "Past studies suggest that SRSF1 could activate MAPK signaling, partially due to the upregulation of interleukin 1 receptor type 1 (IL1R1) through alternative-splicing-regulated mRNA stability to trigger pancreatic ductal adenocarcinoma (PDAC)." (PMID 38735973, 2024).
parasitemia (3 papers, 2016 to 2022). "IL-18 R1 and IL-1R1 were also upregulated over three fold during PbMLFK-KO compared to WT parasite infection." (PMID 27995998, 2016). "Since IL-1R is required for IL-1β produced by inflammasome activation, we next infected 6–8 weeks-old WT and Il1r1−/− mice with a lethal dose (0.5 × 106 iRBCs) of YM, and monitored parasitemia and disease progression." (PMID 30470758, 2018). "Consistently, parasitemia and mortality in DKO mice were markedly increased, compared with those of Il1r1−/− or Casp1−/− mice." (PMID 30470758, 2018). "We also generated Il1r1−/− cDC-DTR mice to deplete cDC population upon diphtheria toxin (DT) administration, and found that cDC depletion at 4 days before YM infection did not change parasitemia and survival, suggesting that cDCs are not responsible for early stage anti-malaria immunity." (PMID 30470758, 2018).
pneumonia (3 papers, 2013 to 2023). An acute, acute and chronic, or chronic inflammation focally or diffusely affecting the lung parenchyma, caused by an infection in one or both of the lungs (by bacteria, viruses, fungi, or mycoplasma.). "However, Mtb-HT1 infected mice that received transient αIL-1R1 treatment developed necrotic pneumonia and histopathological disease like Mtb-LT1, linking T cell priming and ensuant granulomatous response in the lung to IL-1R signaling." (PMID 35173157, 2022).
scrapie (3 papers, 2020 to 2021). A fatal disease of the nervous system in sheep and goats, characterized by pruritus, debility, and locomotor incoordination. "The loss of IL-1R1 gene expression has been shown to increase the survival time of mice during infection with scrapie." (PMID 32806582, 2020). "Among the pro-inflammatory cytokines, IL-1 seems to play a prominent detrimental role in prion-associated neuroinflammation, since knocking-out the IL-1 receptor 1 (IL-1R1) prolongs prion incubation times and delays disease progression in scrapie infected IL-1R1 KO." (PMID 33092220, 2020).
status epilepticus (3 papers, 2020 to 2025). Status epilepticus is defined as a continuous seizure lasting more than 30 min, or two or more seizures without full recovery of consciousness between any of them. "However, whether and how endothelial IL-1R1 modulates neuroinflammatory responses in the pathological process of epileptic seizures and/or status epilepticus (SE) remains obscure." (PMID 38087170, 2024).
type 1 diabetes (3 papers, 2015 to 2022). "Four SNPs with a strong type 1 diabetes association and an eQTL signal were seen in ADAR (encoding RNA-specific adenosine deaminase), IL1R1 (encoding IL-1 receptor type 1), IRF7 (encoding IFN regulator 7) and the OAS gene family." (PMID 33973017, 2021).
Venous thrombosis (3 papers, 2017 to 2021). Formation of a blood clot (thrombus) inside a vein, causing the obstruction of blood flow. "Some studies reported that IL1R1 and IL1R2 SNPs are associated with venous thrombosis and immune and inflammatory disease." (PMID 30672138, 2019). "For example, previous study showed that the haplotype of IL1B, IL1RN, IL1R1, and IL1R2 increased the risk of venous thrombosis, and IL1/IL1Ra, CTLA-4 and Apo1/Fas genes polymorphisms associate with IgA nephropathy." (PMID 28881593, 2017).
acne (2 papers, 2023 to 2024). An inflammatory process of the sebaceous glands which is characterized by comedones, nodules, papules and/or pustules on the skin. "We also found that cg19964325, located in the 5’ UTR of the IL1R1 gene, could be a potential gene for the genetic risk of acne." (PMID 37554505, 2023). "We found that four CpG loci mediated the genetic risk of severe acne, three of which, cg03020863, cg20652636, and cg19964325, were located on the PDGFD gene body, the SH2D6 intron variant, and the 5’ UTR of the IL1R1 gene, respectively." (PMID 37554505, 2023).
acute myeloid leukemia (2 papers, 2022 to 2023). Acute myeloid leukemia (AML) is a group of neoplasms arising from precursor cells committed to the myeloid cell-line differentiation. "IL-1R1 and IL-1RAcP were previously shown to be upregulated in acute myeloid leukemia (AML) and chronic myelogenous leukemia (CML) patients." (PMID 36100613, 2022).
alcoholic steatohepatitis (2 papers, 2020 to 2024). "Studies have shown that deletion of IL1R1 in hepatocytes or macrophage leads to the alleviation of liver inflammation, steatosis, and damage in mice, and the use of IL1Ra benefits patients with severe alcoholic steatohepatitis." (PMID 37634084, 2024).
Amoebiasis (2 papers, 2013 to 2024). "While some significant GO terms were identified in female MIA offspring (‘Amoebiasis’, ‘Cytokine-cytokine receptor interaction’ and ‘Human T-cell leukemia virus 1 infection’), all were driven by the genes interleukin 1 receptor type 1 (Il1r1) and transforming growth factor beta 3 (Tgfb3)." (PMID 38715090, 2024).
Anorexia (2 papers, 2015 to 2016). Lack of desire to eat (loss of appetite). "First, a recent study by Wu and Zhang reported that type 1 IL-1 receptor (IL-1R1) antagonist IL-1RA dose-dependently attenuated both IL-1 beta- and acute DON-induced anorexia." (PMID 26492270, 2015).
anxiety disorder (2 papers, 2021 to 2023). A category of psychiatric disorders which are characterized by anxious feelings or fear often accompanied by physical symptoms associated with anxiety. "Various other genes have been implicated in the efficacy of CBT/iCBT in treating anxiety disorders, such as Glutamate Receptor, Ionotropic Kainate 4 (GRIK4), Hypocretin/hypocretin receptor 1 (HCRTR1), and Interleukin 1 Receptor Type 1 (IL1R1)." (PMID 37497400, 2023). "Cognitive-behavioral therapy (CBT) is an useful psychosocial intervention for anxiety disorders and previous study has reported that the methylation level of IL1R1 was changed in subjects of panic disorder (one of the anxiety disorders) treated with CBT." (PMID 34650599, 2021).
atrophic gastritis (2 papers, 2015 to 2016). "Real-time PCR showed higher expression of IL-1R1 in GC than atrophic gastritis, and IL-1R1's expression level was also connected with Hp infection." (PMID 26870992, 2016).
bladder cancer (2 papers, 2024 to 2025). "We found that TNFRSF12A, IL1R1, ELN and CYP26B1 were overexpressed in bladder cancer cell lines, while NR1H3 and ITIH4 were downregulated." (PMID 38216619, 2024).
bone marrow fibrosis (2 papers, 2022 to 2025). "Here, we show that IL-1 signaling contributes to clonal expansion and progression of bone marrow fibrosis, and blocking of IL-1R1 with anti-IL-1R1 antibodies reduces the MPN disease burden and ameliorates bone marrow fibrosis in a Jak2V617F mouse model of MPN." (PMID 36100596, 2022).